ENSG00000277311
Gene: Miscellaneous RNA gene on chromosome 2 (44,934,055 to 44,934,271, forward strand). Ensembl gene ENSG00000277311.
Gene Ontology:
Biological process: regulation of gene expression